THBS1 (thrombospondin 1)
Diseases named in the same sentence as THBS1 in open-access papers (continued):
Sharing a sentence is not in itself a finding about the gene and the disease.
cancer (continued). "Furthermore, in orthotopically generated CRC models in male mice, THBS1 loss in the TME renders tumors partially sensitive to immune checkpoint inhibitors and anti-cancer drugs." (PMID 37749092, 2023). "Similarly, in multiple cancer types, the expression of THBS1 is silenced through hyper-methylation of its promoter to induce immune escape and EMT." (PMID 37190208, 2023). "This study also identified ITGB1, FBN1, and THBS1 as putative pan-cancer detection biomarkers." (PMID 36010848, 2022). "However, expression of THBS-1 is induced by TGF-β1 in cancer stroma and promotes invasion of oral squamous cell carcinoma." (PMID 35705962, 2022). "However, THBS1 has been reported to promote the attachment of cells to the extracellular matrix, favouring cancer cell migration and invasion." (PMID 35543624, 2022). "THBS1 is overexpressed in a large number of solid tumours, but its role in cancer is controversial." (PMID 35543624, 2022). "Moreover, SPARC, SERPINE1, and THBS1 are reported in the Wikipathways 2019 human database to play a role senescence and autophagy in cancer." (PMID 34064977, 2021). "Interestingly, expression of Thrombospondin1 (THBS1) mRNA, one of the previously identified targets in cancer progression, is significantly increased in Stau1-depleted cells." (PMID 35008641, 2021). "However, recent studies have found that THBS1 is highly expressed in certain malignant tumors and can promote angiogenesis." (PMID 34635636, 2021). "Since thrombospondin-1 stimulates cell migration and may potentially contribute to the spread of cancer, blocking TSP1–CD47 interaction may be another novel therapeutic approach in CTCL." (PMID 34885092, 2021). "Indeed, THBS1 is an inhibitor of both processes in many cancers, while, in others, it acts as a positive regulator." (PMID 35008641, 2021). "The let-7f inhibition and upregulation of antiangiogenic factor thrombospondin-1 may be responsible for the molecular mechanism of cancer cell inhibition." (PMID 34283075, 2021). "Moreover, THBS1 is an activator of TGFβ signaling, and an inhibitor of pro-angiogenic nitric oxide signaling, which plays a role in several cancers and immune-inflammatory conditions." (PMID 32963231, 2020). "It further inhibited expression of THBS-1 in both cancer cell lines." (PMID 32630719, 2020). "Thrombospondin 1 (TSP1) is another ECM glycoprotein of relevance to immune modulation in cancer." (PMID 33187209, 2020). "Similarly to VEGF, the difference in the role of THBS1 in plasma compared to THBS1 stored in platelets is unclear, especially in relation to cancer." (PMID 32421745, 2020). "Therefore, an integral and comprehensive study is needed to probe these controversies to determine the real role of THBS1 in human cancer." (PMID 33244454, 2020). "Some studies have reported that THBS1 can stimulate the malignant invasiveness of cancer." (PMID 31824575, 2019). "NE and CG both promote lung metastasis by degrading anti-cancer protein Thrombospondin 1 (Tsp1)." (PMID 31010242, 2019). "Interestingly, several well-known cancer biomarkers, THBS1, ENO1, and MUC1, were found to be expressed at much higher abundance in exosomes than total membrane proteins." (PMID 30646616, 2019). "In primary OSCC tissues, THBS1 was primarily detected in cancer cells." (PMID 29986759, 2018). "Several THBS1-based compounds are in development for cancer therapy." (PMID 27513329, 2016). "Finally, Thbs1 silencing or overexpression in human cancer cells was shown to decrease or enhance integrin protein levels, respectively, in the intracellular and plasma membrane compartment and thereby modulate cellular adhesion." (PMID 27669143, 2016). "However, metastasis-incompetent cancer cells can foster a metastasis-compatible TME by secreting extracellular factors including thrombospondin 1 to promote niche formation at metastatic sites." (PMID 25857315, 2015).
cancer (continued). "In addition, up-regulation of multiple pro-angiogenic factors enabled carcinoma cells to escape from angiogenesis inhibition by the three endogenous anti-angiogenic molecules thrombospondin-1, endostatin, and tumstatin." (PMID 19788758, 2009). "Moreover, upregulated TIMP3 is associated with Thrombospondin 1 (THBS1) in the protein-protein interaction network, and upregulated TIMP3 may be involved in the ECM–receptor interaction signalling pathway during cancer metastasis." (PMID 38542164, 2024). "THBS1 may inhibit cancer development by suppressing angiogenesis 69-71." (PMID 37771777, 2023). "However, THBS1 expression is increased in many cancers promoting invasion and metastasis." (PMID 37816387, 2023). "Moreover, the expression of THBS1 is closely related to the proliferation of cancer cells." (PMID 37686118, 2023). "Moreover, THBS1 is involved in the cancer cell and metastasis." (PMID 36239104, 2022). "Also, the levels of THBS1 methylation in the non‐cancer control group were examined." (PMID 34390026, 2021). "Successful seeding of cancer cells at secondary organs is just a prerequisite, and the TME at the secondary site may actually restrain ectopic cell survival and expansion as illustrated by neutrophil-mediated killing of cancer cells or thrombospondin 1 secretion by bone marrow-derived Gr1+ cells." (PMID 25857315, 2015). "Recent research has highlighted the interaction between Hippo/YAP signaling and the YAP/THBS1/FAK axis, uncovering new mechanisms by which YAP influences cancer cell behavior through focal adhesion and related pathways." (PMID 40895190, 2025). "MYC activates angiogenesis by increasing the expression of interleukin (IL)-1β, as well as by inhibiting thrombospondin-1 (TSP-1), which facilitates nutrient delivery to the cancer cells." (PMID 40290126, 2025). "Inhibiting YAP–TEAD interaction (e.g., with verteporfin) or targeting FAK or its upstream regulators (THBS1, HMGB1) disrupts this signaling, leading to reduced cancer cell aggressiveness." (PMID 40895190, 2025). "The PI3K-Akt signaling and proteoglycans in cancer were significantly enriched, involving proteins such as COL1A1, FN1, THBS1, FLNA, and ACTB." (PMID 40710368, 2025). "Studies have shown that PRR13 plays an important role in chemotherapeutic resistance by reducing the expression of the pro-apoptotic gene thrombospondin-1 (TSP1), thereby inhibiting taxol-induced apoptosis in cancer cells." (PMID 40099041, 2025). "Although iCAFs are often found in close proximity to cancer cells and engage in active stromal–immune crosstalk, ZFP36 and THBS1 were predominantly enriched in proCAFs." (PMID 41194113, 2025). "Similar to MMP-2, MMP-9 (also known as gelatinase B) degrades gelatin and type IV collagen, and exosomal thrombospondin-1 (THBS1) binds to FAK and MMP-9 to prevent ECM stiffness-dependent cancer invasion." (PMID 38544822, 2024). "KEGG analysis showed that THBS1 participates in PI3K-Akt, ECM-receptor interaction, microRNAs in cancer, and the Rap1 pathway." (PMID 38183097, 2024). "We further confirmed that TGFβ-induced THBS1 interacts with integrin receptor ITGAV, facilitating the migration and invasion of cancer cells in both in vitro and in vivo models." (PMID 39304722, 2024). "Our RNAseq analysis revealed consistent patterns of dysregulation for these biomarkers across all cancer stages, from Stage I to Stage IV, highlighting three of them: fibronectin 1 (FN1), coagulation factor V (F5), and thrombospondin 1 (THBS1)." (PMID 39456895, 2024). "In summary, these data indicate that TGFβ-induced THBS1 and other ECM proteins are involved in the migration and invasion of cancer cells in a TβRI-dependent manner." (PMID 39304722, 2024).
cancer (continued). "Cluster 23 (CD31+ApoE+ EC cells) also exhibited a significant spatial interaction with Cluster 18 cancer cells by S100A10 and Thbs1 secretion." (PMID 39695088, 2024). "Overall, our in vitro, in vivo, and patient data is consistent in that Kaiso plays a regulatory role in THBS1, CD47, and SIRPA, which are each well documented for cancer to evade immune surveillance." (PMID 37190208, 2023). "The most well characterized CD47 interaction partners include thrombospondin-1, integrins, and members of the signal-regulatory protein (SIRP) family, which signal through CD47 to promote various hallmarks of cancer." (PMID 37958404, 2023). "THBS1 can bind to CD47 in hematological tumors, thereby inhibiting the immune response to cancer cells." (PMID 37771777, 2023). "THBS1, a relevant ECM component in many cancers, was shown to induce apoptosis by ligation to CD4734–36." (PMID 36899005, 2023). "Thrombospondin-1 (THBS1) is a matricellular protein highly expressed in inflammatory processes, including cancer." (PMID 37749092, 2023). "CD36, PDK4, and THBS1 were highly expressed in cancer tissues, and G3BP2, PTPRB, and TMEM125 were lowly expressed in cancer tissues." (PMID 36147333, 2022). "The sponge product also inhibits the expression of proliferation-related genes such as CCND1, thrombospondin-1 (THBS-1), TGF-β1, PCNA, c-Myc, and PD-L1 in several types of cancers." (PMID 35705962, 2022). "Overexpression of Runt-Related Transcription Factor-1 (RUNX1) in cancer cells of the replacement lesions, which is mediated by TGF-β1 and thrombospondin 1 (TSP1), enhances cell motility to achieve vessel co-option." (PMID 36430910, 2022). "The expression levels of CXCL12, THBS1, PPBP, GZMB, CD74, and UNC93B1 were higher in the cancer group than in the normal group." (PMID 36211454, 2022). "To further explore the effect of curcumin on macrophages, we also tested the expression of phagocytosis “checkpoints”, such as THBS1, Siglec-G, and SIRP-α, which are involved in suppressing macrophage phagocytosis against cancer cells." (PMID 36359867, 2022). "The elevated expression of THBS1 and WNT3 genes confers cancer cell resistance to therapies through diverse mechanisms." (PMID 36139614, 2022). "CD36, THBS1, and PDK4 were highly expressed in cancer tissues, whereas PTPRB, G3BP2, and TMEM125 were lowly expressed in cancer tissues." (PMID 36147333, 2022). "Secretome analysis following platelet–cancer cell interactions has detected the enhanced release of RANTES (regulated upon activation, normal T-cell expressed and secreted), thrombospondin-1, transforming growth factor-β, and clusterin chemokines." (PMID 36110962, 2022). "Downstream targets of the T3-integrin ανβ3-MAPK pathway, such as matrix metalloproteinases (MMPs), thrombospondin 1 (TSP-1), and spondin-2, are known to enhance cancer cell migration." (PMID 35008863, 2021). "The best-known angiogenic regulators in cancer are vascular endothelial growth factor A (VEGF-A), von Willebrand factor (VWF), and thrombospondin-1 (TSP-1)." (PMID 33809480, 2021). "Platelets secreting thrombospondin-1, and RANTES, modulating cancer cell cycle, DNA damage repair pathways and MAPK levels." (PMID 34095111, 2021). "Particularly, THBS1 and THBS2 have an active effect on the EMT pathway in more than half of cancer types." (PMID 34804159, 2021). "These women are recommended to first respond to a questionnaire and provide information such as age, family history of cancer, etc., and then undergo gynecologic ultrasonography and proteomic analysis of SPARC and THBS1." (PMID 34064977, 2021). "Thrombospondin-1 (TSP1) is a major endogenous anti-angiogenic protein secreted by various cell types, including cancer cells." (PMID 34439212, 2021). "Clusterin, thrombospondin-1, and RANTES secreted by platelet are demonstrated to protect adenocarcinoma cells from anticancer drugs via modulating cancer cell cycle, DNA damage repair pathways and MAPK levels." (PMID 34095111, 2021).
cancer (continued). "The result revealed that Thbs1 participated in “metabolism of proteins”, “focal adhesion”, “PI3K-Akt signaling pathway” and “MicroRNAs in cancer” at same time." (PMID 33479397, 2021). "Recent cancer studies have found that the thrombospondin (THBS) family, including THBS1, THBS2, THBS3, THBS4, and THBS5, play vital roles in the development and progression of human cancers." (PMID 34804159, 2021). "We further probed the changes in cancer dormancy-relevant genes CTSD, THBS1 across pseudo-time, and tissue of origin using Monocle2." (PMID 34579762, 2021). "Thrombospondin 1 (TSP-1) is a strong inhibitor of angiogenesis, promotes inflammatory (‘M1-type’) macrophage recruitment and prevents stemness of cancer cells." (PMID 32481570, 2020). "One study has suggested that SFRP1 plays an additional inhibitory role in breast cancer by blocking the activity of thrombospondin-1 (TSP1), which is involved in the modulation of adhesion and migration of cancer cells." (PMID 32074995, 2020). "The ligand also interacts with thrombospondin-1 (TSP-1), which can directly regulate angiogenesis, nitric oxide signaling, T cells, and cancer stem cell renewal." (PMID 35582455, 2020). "In addition, WTAP also regulates the expression of certain genes associated with cancer cell movement, such as chemokine ligand 2 (CCL2), CCL3, matrix metalloproteinase 3 (MMP3), lysyl oxidase like 1 (LOXL1), hyaluronic acid synthase 1 (HAS1) and thrombospondin 1 (THBS1)." (PMID 32943100, 2020). "In our study, we analyzed the Cancer Cell Line Encyclopedia (CCLE), The Cancer Genome Atlas (TCGA), and the Genomics of Drug Sensitivity in Cancer (GDSC) database, to select six genes (FBN1, FN1, HGF, MMP9, THBS1, and VCAN) as target genes." (PMID 33014013, 2020). "Upregulation of miR-17 can promote cancer growth via aiming E2F1 and increase angiogenesis through thrombospondin-1." (PMID 31032345, 2019). "We have shown that knock-down of HUGL1 in human mammary epithelial cells leads to upregulation of five transcripts that have been linked to cancer stem cells, side population (SP) cells, or increased invasion in cancers (ABCG2, MMP2, ESR1, THBS1 and KRT19)." (PMID 29361610, 2018). "Another ECM component that is capable of sequestering HGF is the thrombospondin-1 (TSP-1), a matricellular protein involved in angiogenesis, inflammation and cancer." (PMID 30352967, 2018). "This confirms the added value of two of four cancer-specific protein biomarkers (CTSD and THBS1) and their complementarity to the standard %fPSA test." (PMID 28767721, 2017). "We also identified two genes, thrombospondin I (THBS1) and PDGFD, which participate in a wide range of signaling pathways that regulate cellular processes involved in cancer genesis and progression." (PMID 27756408, 2016). "Decreased expression of THBS1 and CD44, a cancer stem cell marker, in TPC1 and BCPAP cells with Y15 that were detected by microarray were also validated by Western blotting." (PMID 25277206, 2014). "Increased expression of THBS1 is a prognostic predictor of increased invasiveness in PDAC and correlates with the progression of metaplasia-dysplasia and cancer in oesophagus." (PMID 23372777, 2013). "Of the H2AR29me2 target genes, thrombospondin-1 (THBS1) is of particular interest, being a potent natural inhibitor of angiogenesis and cell migration, dysregulated in several types of cancer." (PMID 21774791, 2011). "Thrombospondin-1 (TSP-1) is a matricellular protein involved in angiogenesis, cancer, and inflammation." (PMID 21765615, 2011). "Both PAR2 and PAR1 activation resulted in up-regulated expression of several genes (CD44, FOSL1, TNFRSF12A, RAB3A, COPEB, CORO1C, THBS1, SDC4) known to be important in cancer." (PMID 21072196, 2010). "Thrombospondin-1 (THBS1) is one of the five members of a family of thrombospondins that mediate the interaction of normal and cancer cells with the extracellular matrix and surrounding tissue." (PMID 20573232, 2010).
cancer (continued). "ThBS1 is known to promote EMT and epithelial plasticity in cancer and tissue regeneration." (PMID 40547038, 2025). "In addition, thrombospondin-1 (THBS1), an extracellular matrix protein, is induced by TGFβ and promotes migration and invasion of cancer cells." (PMID 39695086, 2024). "Both THBS1 and THBS2 share the TSR2 domain that interacts with the epidermal growth factor receptor (EGFR), which in turn is known to activate the PI3K/Akt/mTOR downstream signal pathway, known to be involved in cancer cell growth and survival." (PMID 38339060, 2024). "In addition, thrombospondin-1 (TSP-1), a large glycoprotein present in the basement membrane surrounding mature blood vessels, has also been shown to regulate cancer cell dormancy and metastasis 104-106." (PMID 38817858, 2024). "However, THBS1 also acts as a transcriptional activator of TGF-β to activate the TGF-β signaling pathway, thus promoting cancer development." (PMID 37771777, 2023). "Finally, the balance of pro- and anti-angiogenic factors produced by CAFs, such as VEGF for the former and thrombospondin-1 (TSP-1) for the latter, is also involved in the regulation of cancer cell dormancy." (PMID 37173977, 2023). "myCAFs may also express other matrix proteins including THBS1 (thrombospondin 1), THBS2, and TNC (tenascin C, a matrix protein), to communicate with immunocytes, smooth muscle cells, cancer cells, and plasma cells through CD44, integrin (α3β1), and SDC1." (PMID 35986392, 2022). "ITGB1, FBN1, and THBS1 have not been coherently identified as putative “pan-cancer” early detection biomarkers because a similar study to this one has not been conducted previously." (PMID 36010848, 2022). "Moreover, CD36 binds and recognizes thrombospondin-1 (TSP-1), an extracellular matrix protein that was shown to play a multifaceted role in cancer as part of the tumor microenvironment." (PMID 35054787, 2022). "We found 16 proteins including HP, PKM, ANXA2, THBS1 that are differentially abundant in GBC tissue (literature search and unpublished data from our lab), in plasma and plasma-derived EVs from GBC or other cancer patients." (PMID 36505879, 2022). "Additionally, ESCC biomarkers identified in previous study, such as ACTA2, ANXA1, HSPA9, THBS1 etc. were also detected in EESCC, indicating the key events in advanced-stage cancer happened as earlier as in the early-stage cancer." (PMID 35397555, 2022). "Three selected proteins (QSOX1, THBS1 and EDIL3) were detected in CRC patient pEXOs and might be useful candidates in early cancer diagnostics engaging non-invasive liquid biopsy." (PMID 33802764, 2021). "Nevertheless, THBS1, FN1, TNC, COL1, and COL4 were expressed in both stroma and cancer cells." (PMID 34121340, 2021). "Compared with THBS1, researches on THBS2 are limited in human cancer and especially rare in CRC." (PMID 33244454, 2020). "Other studies show that MYC activates angiogenesis by increasing the expression of Interleukin 1β and VEGF and suppressing Thrombospondin-1 (TSP-1), thereby facilitating the delivery of nutrients to cancer cells and allowing for the escape of cancer cells into the bloodstream." (PMID 33081056, 2020). "Among the commonly upregulated LD+ associated genes in GBM cells and patient tumors, we found several hypoxia-related, key effectors of angiogenesis, macrophage recruitment and stromal remodeling in cancer (e.g. VEGF-A, TGF-β1, IL1β, ADM, IGFB3, LOX, CA9, THBS1, PLODs, ID2)." (PMID 31174567, 2019). "THBS1 attracted our attention because of its EGF‐like motifs, its function in the modulation of the ECM, angiogenesis, and its implication in SCC and other types of cancer." (PMID 31580518, 2019).